CD68 (CD68 molecule)
Diseases named in the same sentence as CD68 in open-access papers (continued):
Sharing a sentence is not in itself a finding about the gene and the disease.
cancer (continued). "Moreover, in IDC paths #1 and #2, marker genes for endothelial cells (VWF and PECAM1), lymphocytes (CD4), macrophages (CD68), chemokines (CXCL12 and CCL5), and chemokine receptors (CXCR4) were expressed highly at the intermediate stages of cancer progression." (PMID 39965034, 2025). "Moreover, spatial transcriptional data obtained from the STOmics DB database revealed a spatial overlap between SUSD3 expression and markers of M2 macrophages, namely CD163 and CD68, within HINSC cancer tissues." (PMID 40191190, 2025). "Another study on uterine cervical cancer showed that high splenic FDG uptake was related to high immune cell densities in the cancer tissue, especially for immune cells expressing CD20 (a marker of B lymphocytes) and CD68 (a marker of monocyte cell types, including macrophages)." (PMID 38790906, 2024). "GEO data (GSE35261, GSE30784, GSE26549, and GSE85195 combination), including 56 normal tissues, 78 OLKs, and 212 OSCCs, revealed a higher expression of IDO1 in OLK and OSCC than in para-cancer tissue and a positive relationship between IDO1 and CD68 expression in OLK." (PMID 39239507, 2024). "We should note that none of these authors divide CD68 into CD68-IT and CD68-ST, and no one has considered their specific role in cancer." (PMID 39201801, 2024). "Among them, many international cohorts of cancer patients have shown negative prognostic value for TAMs expressing CD68, CD163, CD204, CD206, MARCO, and stabilin-1." (PMID 39516356, 2024). "As the C1QA-C expression in cancers was mainly detected in CD68+CD163+ macrophages, the synthesis of complement C1q components analysed at the bulk RNA level can potentially be used to estimate the amount of pro-tumoural CD68+CD163+-like macrophages." (PMID 36724681, 2023). "Nevertheless, there were no significant survival differences for both the density of CD68+ MØs in the stroma and carcinoma nest." (PMID 37254126, 2023). "Because PD-L1-negative EpCAM+ cancer cells, low PD-1 expressed CD8+T cells, and remarkably increased CD14+CD68+CD163+TIM-3+ macrophages were observed in MPE with disease progression, TIM-3 blockade therapy might be applicable to treatment." (PMID 36293034, 2022). "In our model, because the expression of CD68 was detected in cancer cells and did not appear to be restricted to macrophages, it was not considered a TAM marker." (PMID 35158887, 2022). "We further analyzed the expression patterns of CD68 and CD204 in normal lung and cancer tissues." (PMID 36077342, 2022). "Finally, we analyzed three public databases (CellMiner, CTRP, and Genomics of Drug Sensitivity in Cancer [GDSC]) to identify small molecules and sensitive drugs based on CD68 expression." (PMID 35550532, 2022). "YKL-40 gene expression was primarily increased in the fibroblast (gene annotation: COL1A, BGN, DCN), myeloid (gene annotation: CD68, LYZ, AIF1), cancer (gene annotation: EPCAM, KRT7, KRT18), and B-cell (gene annotation: CD79A, CD79B) populations in cancer tissue compared to healthy tissue." (PMID 35631632, 2022). "Nonetheless, the CD68 marker does not discriminate between M1 or M2 macrophage phenotypes or immune checkpoint molecules exploited by cancer cells to block macrophage activity." (PMID 35406573, 2022). "In addition, we quantified multiple combinations of cells positive for CD68, CD163, PD-L1, and CK in the stromal area, and compared the cell counts of sTAM subpopulations among the three cancer subtypes." (PMID 36362023, 2022). "In contrast, CD68 expression was strongly and positively correlated with CNV in most cancer types." (PMID 35979347, 2022). "Furthermore, the relationship between CD8, CD68, and CD163 in these cancers was verified by multiplex immunofluorescence staining." (PMID 36389798, 2022).
cancer (continued). "Based on our findings, we concluded that EMR1 upregulation in cancer cells is regulated by TAM and has a significant relationship with lymph node metastasis, and the combined EMR1-TC+CD68+CD163+ expression can be used as a prognostic indicator in patients with CRC." (PMID 36551877, 2022). "The cancer genes are composed of genes that code for HER2 (HER2 and GRB7), oestrogen genes (ER, PGR, BCL2, and SCUBE2), proliferation genes (MKI67, STK15, BIRC5, CCNB1, and MYBL2), and invasion genes (MMP11 and CTSL2) as well as GSTM1, CD68, and BAG1." (PMID 36042999, 2022). "Thus, we determined the incidence of CD14+ monocytes, and CD68+, CD163+ and MAC387+ TAMs in the cancer tissues of HCMV+ IBC patients." (PMID 35847899, 2022). "However, our data highlight the pronounced heterogeneity of BTK protein expression in distinct cell types including cancer stem-like cells (SOX2), TAMs (CD163) and microglia (CD68)." (PMID 34645618, 2021). "The CD163 staining pattern showed that the less nonspecific staining of carcinoma cells and other inflammatory factors in a cleaner background than CD68." (PMID 33928349, 2021). "STAT3 correlated with CD68 and CD163, meaning that STAT3 might correlate with M2 macrophage to regulate cancer development." (PMID 32486001, 2020). "Next, we showed that CD68/HLA-DRII-positive cells expressed IL-34 in both TICs and LPMCs preparations, even though the fraction of IL-34-positive cells was significantly higher in cancer samples." (PMID 33298879, 2020). "Importantly, CD68 macrophages expressing CXCL5 were found within the cancers and with significantly higher numbers in the stroma around the nests of cancer cells." (PMID 33149188, 2020). "Thus, the numbers of CD68+ macrophages, as well as the numbers of macrophages positive for M2 markers (CD163 and CD204) in borderline and malignant tumors were significantly higher in both serous and mucinous ovarian tumors than in benign tumors." (PMID 33194645, 2020). "In contrast, poor OS correlated with high expression of CD68 in ER− cases, while high expression of CD163 was associated with improved OS in ER− cases but not in ER+ cancers." (PMID 33194645, 2020). "In both oropharyngeal and nonoropharyngeal SCC, CD68+ macrophage infiltration increases between dysplastic tissues and carcinoma; the macrophage infiltration density is higher in the advanced stages." (PMID 31510065, 2019). "In addition, CD68, CD163 and HO-1 expression was also observed on AMs in lung tissue adjacent to the cancer margin." (PMID 26900851, 2016). "We further confirmed a strong positive correlation between NLRC4 expression with myeloid lineage markers from the TCGA data set, including specific macrophage marker CD163 and common myeloid markers CD68 and CD33, suggestive of a myeloid origin of NLRC4 in human cancer." (PMID 27708283, 2016). "Recent studies have postulated that TAMs triggers EMT through regulation of different signaling pathways in cancer, with E-cadherin showing a negative correlation with CD68+ macrophage density." (PMID 27462782, 2016). "A similar trend, although not being significant, was observed for CD68+ macrophages located in close proximity to carcinoma cells (H3) as well as to FoxP3+(CD4+) T cells (F)." (PMID 24797069, 2014). "In the context of the present results, it is also important to acknowledge that, there is some recent evidence that CD68+ can be expressed on non-myeloid cells including carcinomas." (PMID 22240784, 2012). "Infiltrated CD11b+/CD68+ TAM is intensely involved in OUBC-induced lymphangiogenesis and lymphatic metastasis and therefore TAM could be the bridge between primary cancer and SLN." (PMID 21481239, 2011). "For instance, the correlation between CD68 and PDCD1 (PD-1) implies that CD68-expressing macrophages may contribute to the immunosuppressive TME by upregulating PD-1/PD-L1 signaling, a well-known mechanism of immune evasion in cancer." (PMID 40918116, 2025).
cancer (continued). "Epigenetically escaped cancers (without genetic escape), when compared to nonescaped biopsies, showed an enrichment of CD68+ cells (macrophages) and CD45RO+ cells (memory T cells), suggesting an association between SCAA-loss of antigen presentation and the TME." (PMID 41193656, 2025). "There were greater numbers of PD-L1- and IL-10-expressing macrophages (CD68+ cells) and PD-L1- and IL-10-expressing dendritic cells (CD11c+ cells), as well as PD-L1- and IL-10-expressing macrophages in the PBMC and cancer mucosa, in AGC patients than in EGC patients." (PMID 38197259, 2024). "In these hemorrhagic regions, we found an increased Cd68 signal, confirming macrophage infiltration, superimposed by upregulated expression of Hmox1 and Arg1, the latter of which is the archetypal marker for procancerous and immunosuppressive TAMs in mice, similar to CD163 and SPP1 in human cancers." (PMID 38060331, 2023). "In addition, CD47 overexpression by cancer cells was directly related to SIRPα expression by TAMs and not with CD68+ TAMs, showing that an interplay between CD47 expressing cancer cells and the SIRPα+ Μφ exists in NSCLC." (PMID 35406573, 2022). "By analysing the transcriptome data of 1100 Breast Invasive Carcinoma (BRCA) samples in The Cancer Genome Atlas Program (TCGA) database, we found that the mRNA expression level of SIPA1 positively correlated with macrophage abundance and pan-macrophage marker CD68." (PMID 35453742, 2022). "Furthermore, we also used multiplex immunofluorescence staining to verify the co-expression of CD147 with macrophages (CD68) and M2 macrophages (CD163) in these cancers, which CD68 was marked red, CD163 was marked green, CD147 was marked purple, and DAPI was marked blue." (PMID 35464411, 2022). "In addition, OSCAR expression was positively correlated with infiltrating levels of TAMs in 20/20 types of cancer, especially BRCA (CCL2, r=0.428; CD68, r=0.769; IL10, r=0.542), COAD (CCL2, r=0.561; CD68, r=0.624; IL10, r=0.536), and THCA (CCL2, r=0.612; CD68, r=0.870; IL10, r=0.597)." (PMID 34093786, 2021). "Among CD68+CD163+ TAMs also expressing the recently identified TREM2 marker, we could identify a CXCL10+IRF1+STAT1+ M1-type Mφ population (Cluster 9) shared between all cancer types." (PMID 34220848, 2021). "Indeed, CD163 or CD68 macrophages in the stroma rather than in the cancer cell nests have been shown to correlate with a poor prognosis." (PMID 33149188, 2020). "Thus, we speculate that the interaction of the CD68+ PD-L1+ cells and CD8+ PD-1High cells plays a role in inhibiting the anti-cancer response." (PMID 33228682, 2020). "Interestingly, with exception of CD68+ cells, all other subtypes of TILs infiltrating p16Ink4a-negative cancers did not influence the clinical outcome of patients." (PMID 28515351, 2017). "So far, the reasons for such discrepancies using similar methodology are unclear, however, some evidence declares macrophage markers, such as CD68 may be expressed by other non-myeloid tissues in cancer." (PMID 28427165, 2017). "Using CD68 (a specific marker of monocytes/macrophages), it was demonstrated that the cells at the IF most strongly staining for cathepsin D were of monocytes/macrophage phenotype rather than being cancer cells." (PMID 22919486, 2012). "Interestingly, among pan-cancer, LGG showed the most significant correlation between GLA with CD86 (P=4.52e-27), CSF1R (P=8.17e-09),CCL2 (P=3.98e-14), CD68 (P=2.37e-34), IL10 (P=3.29e-21), IRF5 (P=8.5e-25), CD163 (P=3.8e-26), VSIG4 (P=9.17e-16) and MS4A4A (P=1.39e-21)." (PMID 37057282, 2023). "Classically activated macrophages expressing CD68 (M1) are correlated to antigen presentation and inflammatory response, whereas alternatively activated macrophages expressing CD163 (M2) may be involved in cancer growth, angiogenesis, metastasis and therapy resistance." (PMID 36982316, 2023).
cancer (continued). "In addition, CD68 was found to be closely correlated with immune infiltrates in the TME and could a promising immunotherapy target that positively correlates with other checkpoint proteins in pan-cancer." (PMID 35550532, 2022). "CD68 is used as a prototype macrophage marker, but it does not discriminate between M1 and M2 macrophages; however, it continues to be used in conventional pathology, explaining the ambiguous results observed when relating CD68 to the cancer response and pCR31." (PMID 35562400, 2022). "Our analysis revealed that VISTA is predominantly expressed by macrophages (CD68 +) and neutrophils (MPO +), while cancer cells (CK11 +) and fibroblasts (αSMA +) showed lower to no expression of VISTA." (PMID 40316725, 2025). "Our results uncover a principle in AML disease suggesting cancer stem cell-driven regeneration is not solely cell autonomous in nature and involves other complex cellular elements exemplified by CD74+CD68+ RECs." (PMID 38582086, 2024). "Within this study, we observed that TNBC tissues showing high macrophage infiltration, evaluated using CD68 as a macrophage marker, presented ID4 protein expression not only in cancer cells but also in cells of the leukocyte infiltrate." (PMID 32054109, 2020). "The pathway, ‘Molecular Mechanism of Cancer’, was found to be altered for the microRNAs that correlated with the presence of CD3+, CD45+, CD8+, and CD68+ lymphocytes as well as infiltrating adipocytes, but not CD4+ lymphocytes." (PMID 28145100, 2017). "To compare cancer immune surveillance (represented by TILs: CD8+, CD4+, FOXP3+, CD56+, TAMs: CD68+ and GZB+ cells) in p16Ink4a -positive and negative primary tumors we analyzed mononuclear infiltrates within cancer nests only." (PMID 28515351, 2017). "CD68 and CD163 expression was not confined to the infiltrating TAMs, but also detected in cancer cells." (PMID 26769084, 2016). "This study was designed to investigate the prognostic role of CD68+, CLEVER+ macrophages, and CLEVER+ lymphatic vessels in CRC; however, the predictive role of these factors could not be examined because of the lack of detailed cancer treatment data for our patient cohort." (PMID 34885098, 2021). "In addition, compared to patients with cancer not treated with ICI therapy, the inflammatory composition of coronary plaque in patients treated with ICIs has been shown to favor a lymphocyte‐predominant phenotype with an increased CD3/CD68 ratio, which may lead to plaque progression and instability." (PMID 40296380, 2025).
infection (142 papers, 2007 to 2026). The state of being infected such as from the introduction of a foreign agent such as serum, vaccine, antigenic substance or organism. "To determine if there is an alteration in synaptic pruning activity between infection routes, we assessed the gene expression of key synaptic pruning markers C1qa and CD68, markers linked with ‘eat-me signals’." (PMID 35898505, 2022). "One study reported that Kupffer cells that express CD68 support the entry of sporozoites to cause infection, while another showed that Kupffer cells that express triggering receptor expressed on myeloid cells 2 (TREM2) are able to reduce hepatocyte infection." (PMID 34271941, 2021). "At 7 days post-infection, M. mass-infected cells showed lower expression of CD68 (pan-macrophage marker present on lysosomal-associated membrane proteins), CD206 (mannose receptor) and CD163 (scavenger receptor) than non-infected cells." (PMID 27489303, 2016). "From 3 days after infection with SIVmacC8 increased levels of CD68-expressing cells were present, predominantly associated with blood vessels within the cerebrum and midbrain." (PMID 27258396, 2016). "In addition, markers (TLR4, CD68, Tyrobp and Cx3cr1) associated with microglial activation were significantly upregulated post infection." (PMID 38093309, 2023). "Similarly, we find that primary SVV infection causes increased CD68 and MHC-II expressions on SGC and, possibly, restricted SGC proliferation in ganglia along the entire neuraxis." (PMID 26676825, 2016). "Infection of both immunodeficient mice results in increases in viral RNA, but only Stat1 KO mice can develop inflammatory foci and have increased number of CD68 +cells in the heart tissue." (PMID 40304490, 2025). "Lung IHC staining revealed that Delta infection resulted in significantly greater pulmonary recruitment of CD68+ macrophages as well as Ly6G+ neutrophils than the other two variants at both timepoints." (PMID 40686017, 2025). "CD68 staining indicated greater infiltration of macrophages after infection of WT or complement strains than modA knockout strain." (PMID 39813328, 2025). "Nevertheless, the distribution of infection in CD68+ myeloid cells in the brain is uneven, making it challenging to compare sizes of brain reservoirs when looking to single biopsies." (PMID 40284910, 2025). "Infection with L. (L.)amazonensis resulted in an increase in CD68+ cells in the dermal inflammatory infiltrate." (PMID 38966642, 2024). "Flow cytometry analysis showed a significant increase in the red pulp macrophages (F4/80high CD68+ CD11b+) of PbHMGB1KO-infected mouse spleen on Days 7 and 9 post-infection." (PMID 39341498, 2024). "These immune molecules are mainly associated with the recruitment of monocytes/macrophages, in keeping with the observation that animals had a higher frequency of macrophages (CD14+ CD68+) in peripheral blood three weeks post-infection with MTB." (PMID 37261336, 2023). "Immunofluorescent assessment of CD68+ macrophages in the mid-ileum tissue from each cow showed animals in the clinical stage of infection had significantly greater numbers compared to subclinical (P < 0.05) and JD- cows (P < 0.05)." (PMID 36816182, 2023). "Consistent with the gene expression we observed, the CD68+ macrophages in the colon were increased with infection in Tln1fl/fl tissues, but were significantly less abundant in infected Tln1Δmye mice." (PMID 38102166, 2023). "One study suggested that neutrophils are recruited as early as 1 day post-infection and that their recruitment persists at 2 days post-infection alongside the arrival of Iba1+ and CD68+ cells." (PMID 37529051, 2023). "Immunohistochemical results found CD68 mainly in the cytoplasm of glomeruli and tubulointerstitium, and that the infection of macrophages in the kidney tissue of CGN rats was increased, while AS-IV was a dose-dependent way to reduce the inflammatory response." (PMID 37529109, 2023).